IL1B (interleukin 1 beta)
Diseases named in the same sentence as IL1B in open-access papers (continued):
Sharing a sentence is not in itself a finding about the gene and the disease.
infection (continued). "At 2–3 months post-infection lung pathology in mice deficient for IL-1α or for IL-1β progressed with reduced free alveolar space, increased inflammatory cell infiltration, acid-fast bacilli abundance and oedema, as compared to wild-type mice, but still little necrosis." (PMID 25400917, 2013). "Notably, IL-1β and IL-18 secretion are abrogated during infection of NLRP3-deficient (Nlrp3−/−) BMDMs with ΔflaA Lp in both primed and unprimed macrophages." (PMID 23762026, 2013). "However, when infected with double mutant of VopQS (ΔtdhASΔvopQS), the IL-1β release in infected NLRP3-deficient macrophages was enhanced to a similar extent as that upon infection with ΔtdhΔh1." (PMID 23357873, 2013). "However, caspase-1−/− mice are more susceptible to some infections than IL-1β−/−IL-18−/− mice, underscoring the importance of additional caspase-1 substrates that alter the immune response." (PMID 24367258, 2013). "TNF deficient mice rapidly lost weight and succumbed by 6 weeks of infection with highly inflammed lung, spleen and liver, while IL-1R1 and IL-1α plus IL-1β deficient mice survived systemic M. bovis BCG infection with lung, spleen and liver weight similar to wild-type mice at 6 and 11 weeks." (PMID 25400917, 2013). "IL-1β is a pivotal inflammatory mediator, produced by PAMPs (Pathogen-associated molecular patterns)-activated cells of innate immune system, driving the host response to control infection or lead to tissue injuries." (PMID 24223208, 2013). "In addition to influenza virus RNA, the IAV M2 ion channel protein has been implicated as an activator of the inflammasome complex, causing the release of mature IL-1β during infection." (PMID 23737748, 2013). "However, IL-1α or IL-1β deficient mice survived to a more chronic infection and lung inflammation was gradually increased in these animals 2 or 3 months post-infection." (PMID 25400917, 2013). "This time point was chosen because we previously observed substantially decreased IL-1β protein levels in S. aureus-infected skin of IL-1R-deficient mice compared with wt mice at 6 hrs after infection and the difference in mRNA levels of IL-1β likely preceded the changes in IL-1β protein levels." (PMID 23209417, 2012). "This interaction may constitute a critical component to effective host defense and diminishing the capacity of host cells to respond to IL-1β may leave the host susceptible to infections by pathogens such as P. aeruginosa." (PMID 22649552, 2012). "We hypothesized that elevated production of IL-1β (2-3-fold over wild type) in response to infection was a major cause contributing to accelerated mortality and was likely attributable directly to neutrophils lacking the inhibitory co-receptor CEACAM1." (PMID 22496641, 2012). "IL-1β-deficient mice show broad host susceptibility to various infections." (PMID 22985464, 2012). "This is illustrated by the findings that compared to ΔSTY/ΔPopB, infection with ΔSTY leads to higher mortality, reduced bacterial clearance, and non-apoptotic killing of alveolar macrophages, which is associated with the production of pro-inflammatory IL-1β." (PMID 22844497, 2012). "However, cell death associated with IL-1β release is not only dependent upon infection with NLRC4-activating pathogens." (PMID 22019906, 2011). "Importantly, we extend these prior findings and demonstrate here for the first time that IL-1β is required for protection from infection bestowed by LT-responsive alleles of Nlrp1b." (PMID 22241984, 2011). "If TNF-α and IL-1β were critical host-components leading to the attenuation observed in mice infected with CO92ΔyopH, then it would not be unreasonable to predict that mice deficient in these molecules would be more sensitive to infection with CO92ΔyopH." (PMID 20565713, 2010). "IL-1β cleavage is a hallmark of inflammasome activation, and we observed significant Pycard, Nlrp3, and Casp-1-dependent inflammasome activation during in vitro infection of cultured cells." (PMID 20808838, 2010).
infection (continued). "We hypothesize that Nlrp1bS-mediated IL-1β release and its associated cytokine and chemokine burst may be the initiating events providing a protective response against spore infection in a complement-independent manner." (PMID 21170303, 2010). "Cancer patients undergoing treatment with systemic cancer chemotherapy drugs often experience debilitating fatigue similar to sickness behavior, a normal response to infection or tissue damage caused by the production of the inflammatory cytokines IL-1β, TNF-α, and IL-6." (PMID 18523641, 2008). "The analysis revealed a significant upregulation of tumor necrosis factor-alpha (TNF-α) and interleukin-1 beta (IL-1β) in the PbA-infected untreated group, compared to the uninfected control group (p < 0.05), indicating a heightened inflammatory response associated with infection." (PMID 40892845, 2025). "However, this variant infection induced a lower amount of Interleukin 1β (IL-1β) and macrophage inflammatory protein-1α (MIP-1α) compared to the wild-type, In the other hand, the Alpha variant triggered a considerable level of TNF-α (14.73 pg/mL) and a modest rise of IP-10 level than wild type." (PMID 38568894, 2024). "We then tested whether loss of IL-1β affects infection-induced mortality." (PMID 38236896, 2024). "However, higher levels of IL-1β were detected in hypoxia–reoxygenation groups, indicating this cytokine is most likely released not by the virus itself but rather by hypoxia or hypoxia–reoxygenation, which is also caused by the infection." (PMID 38068877, 2023). "Despite the fact that the trial was not empowered to study the role of IL-1 inhibitors in OA, and was interrupted because of the increased infection risk, such data support the hypothesis of a critical role of cytokines, especially IL-1β, and inflammation in the pathogenesis of OA." (PMID 37362206, 2023). "Additionally, the analysis of SAPS-related inflammatory cytokines and chemokines in the supernatant of the infected lung slices revealed that infection with the omicron variant exclusively triggered an increased secretion of IL-1b, IL-6, IL-8, TNF-α, and IL-1β." (PMID 38095608, 2023). "In addition, the suppression of BDNF/TrkB signaling by the infection was reversed by administration of the anti-inflammatory cytokine IL-1Ra (interleukin 1-specific receptor antagonist), suggesting a causative role of IL-1β in the infection-evoked reduction in BDNF at the hippocampal synapses." (PMID 35887075, 2022). "Caspase-1 activation usually leads to maturation and release of the proinflammatory interleukin 1β (IL-1β), which can recruit neutrophils and macrophages to sites of infection, we thus tested whether mutation of c3564/c3565 and hlyA influences IL-1β release during UPEC-induced pyroptosis." (PMID 34653218, 2021). "Inflammasome is a functional complex assembled in response to infection or tissue injury, which senses signals from pathogen-associated molecular patterns (PAMPs) or danger-associated molecular patterns (DAMPs) to generate active caspase-1, which converts IL-1β into its mature active form." (PMID 34771641, 2021). "In contrast, module 3 (M3) segregated in a different cluster of cytokines that include low IL-1β, IL-2, IL-12, moderate IL-17, IL-21, and high IFNγ, GM-CSF that were associated with low levels of lymphocytes and low titers of total IgG and IgG1 in the acute phase of infection." (PMID 33815363, 2021). "However, systemic neutralization of IL-1β by Canakinumab may cause severe and undesirable adverse events, especially oppurtunistic infections." (PMID 34290297, 2021). "The early infection (3 dpc) triggered a strong transcriptional up-regulation of many immune genes in different organs including those encoding pro-inflammatory cytokines IL-1β, IL-6 and TNFα and other cytokines involved in the development of adaptive immunity (IL-8, IL-10, IL-22, IL-17C2, INFγ)." (PMID 34497310, 2021).
infection (continued). "Therefore, identification of ZBP1-regulated TRIFosome formation, CASP8 activation, and IL-1β production provides novel points of regulation that could be relevant in the context of various pathogenic infections." (PMID 33397971, 2021). "It is important to note that, generally, biologics targeting the NLRP3/IL-1β pathway target secreted IL-1β directly, like Canakinumab to suppress its inflammatory responses, which poses a serious risk of fatal infection, as IL-1β cannot be produced in response to an infection." (PMID 34439904, 2021). "However, while cytotoxicity mediated by CD8+ T cells and Granzyme B have been associated with pathology in CL, IL-1β seems to have a dual effect as this cytokine may have a protective role in the early phase of the infection in mice." (PMID 32851099, 2020). "Therefore, our data suggest that Atg5 contributes to the intracellular infection of R. australis in primary mouse macrophages in close association with downregulation of the inhibitory effect on rickettsiae mediated by autocrine-secreted IL-1β." (PMID 30297526, 2019). "Therefore, it is reasonable to deduce that IL-1β and the NLRP3 inflammasome are important for the control of the infection caused by Leishmania, and also that the parasite has developed mechanisms to subvert the immune system, interfering with IL-1β synthesis/response." (PMID 31233552, 2019). "Despite IL1-β is an important mediator of early infection responses and an important cytokine linked to inflammation, its down-regulation after 72 h of infection, as it is shown in this work, could indicate decrease in the innate inflammatory responses at this point." (PMID 31046823, 2019). "Our current work indicates that the pro-inflammatory cytokine load, particularly IL-1β, is likely to push naïve cells to a more susceptible phenotype, with bystander cells sustaining higher viral load than naïve cells, particularly during the early stages of infection." (PMID 30101649, 2018). "Lower IL-1β secretion by PBMC was associated with peripheral infection at delivery and lower IL-6 secretion by PBMC was associated with placental infection during pregnancy, supporting the hypothesis that these pro-inflammatory cytokines may contribute to control maternal parasitaemia." (PMID 29743113, 2018). "As compared to C57BL/6, Il9R−/− mice showed a reduced inflammation in the initial phase of infection, but an increased susceptibility in a later phase, as indicated by fungal burden, inflammatory cell recruitment in the vaginal fluids and mucosa and IL-1β production." (PMID 30515173, 2018). "Furthermore, expression of IL-1β mRNA was equivalent in wild-type and gp91 phox deficient cells in response to infection indicating that the increased bacterial burden was having a direct effect on inflammasome activation, and was not just due to increased priming." (PMID 28570638, 2017). "It is also of interest, as infection was raised as a possible cause of AD, immunocompetent individuals rarely develop pro-inflammatory antifungal immune responses because as among many other pro-inflammatory IL1-β mediates MDSCs recruitment and modulate antifungal immune response." (PMID 28736551, 2017). "The increase in IL-1β, IL-6, and CXCLi2 transcription in the spleen and cecal tonsils shows that like S. Typhimurium and other broad-range serovars, S. Virchow elicits a strong immune response in the chicken, causing a rapid inflammatory response upon infection." (PMID 26664914, 2014). "Neutrophils from ASC-deficient mice had a 58% decrease in IL-1β production in response to S. aureus compared with neutrophils from wt mice, indicating that the majority of IL-1β produced during the S. aureus in vitro infection was dependent on the inflammasome component ASC." (PMID 23209417, 2012).
infection (continued). "Although patients with MyD88 or IRAK-4 deficiency may recruit neutrophils to the site of infection, they cannot respond to neutrophil-derived IL-1β to amplify the neutrophilic response, providing a potential explanation for their selective predisposition to pyogenic infections." (PMID 23209417, 2012). "Pro-IL-1β can also be processed into biologically active molecules by proteases from S. aureus and Candida albicans suggesting that extracellular processing may also occur at inflammatory lesions caused by infection." (PMID 22019906, 2011). "However, aflagellar serovars S. Pullorum and S. Gallinarum cause more severe infection than flagellar serovars in chicken because of aflagellar S. Typhimurium could avoid the TLR5 regulation of IL-1β expression and polymorphonuclear cell infiltration in gut." (PMID 20307324, 2010). "However, IL-1β deficient mice are as resistant to L. monocytogenes infection as wild-type mice, suggesting that other inflammatory cytokines mediate innate immune control of this infection." (PMID 18769721, 2008). "Interleukin-1β (IL-1β) is a critical mediator of the immune response to infection, whose excessive release can drive remote organ injury and dysfunction." (PMID 41758390, 2026). "Infection of the BLEs with Mmm stimulated the production of some pro-inflammatory cytokines and mediators, including IL-1β, COX-2, 5-LOX and iNOS." (PMID 41901722, 2026). "In p62-deficient macrophages, we observed reduced expression and secretion of key cytokines, such as IL-1β, TNFα and IL-6, early during infection." (PMID 41583695, 2026). "The ΔvipA1-hcp1 double mutant showed heightened IL-1β levels at 4 h (P < 0.0001) and 8 h (P < 0.01), with sustained IL-8 and IL-6 overexpression across all infection stages (P < 0.0001; P < 0.01)." (PMID 41347512, 2026). "Complementation with pBAH001 or pBAH002 partially rescued production of IL-8, IL-13, IFN-γ, IL-1β, and IL-6, with greater cytokine production occurring with ΔflgB (pBAH001) infection compared to ΔflgB (pBAH002)." (PMID 41459941, 2026). "Infection with the mT3Sf::OspF strain also suppressed NLRC4-dependent IL-1β processing induced by the synthetic NAIP–NLRC4 agonist NeedleTox." (PMID 41533441, 2026). "Compared to the WT strain, the ΔvipA1 mutant significantly elevated IL-1β mRNA levels at 1 h (P < 0.05) and 4 h (P < 0.0001) post-infection and increased both IL-8 and IL-6 mRNA levels at 4 h (P < 0.001)." (PMID 41347512, 2026). "The IL-1β is a potent pro-inflammatory cytokine essential for host defense responses to infections and injuries." (PMID 40145967, 2026). "We found Aph infection induced the expression of the hepcidin mRNA and protein, and strong IL-6, IL-1β, and TNF-α mRNA expression by host cells." (PMID 42294677, 2026). "Infection with contemporary reassortant lineages also induced pro-inflammatory responses, characterized by consistent upregulation of IL-1β across tissues." (PMID 42238877, 2026). "We observed a significant decrease in the expression of IL-1β, TNFɑ and IL-6 in p62-depleted macrophages compared with WT macrophages only at 5 h post-infection." (PMID 41583695, 2026). "Cytokines with the greatest contributions to PC1 included IL‐6, IL‐1β, and IFNγ, particularly among samples with secondary infection." (PMID 41488232, 2026). "Concurrently, infection triggered a pronounced pro-inflammatory response, with mRNA levels of IL-1β, IL-6, IL-8, and TNF-α significantly upregulated." (PMID 41584086, 2026). "Infection with all the multi-deletion mutants except sap2∆/∆ hgc1∆/∆ (GM-CSF, IL-1α, and IL-1β) and sap2∆/∆ ece1∆/∆ (IL-1α) led to a significant reduction in cytokine secretion." (PMID 41294335, 2026). "The NLRP3 inflammasome mediates the maturation of IL-1β and IL-18 primarily in myeloid cells, thereby shaping inflammatory and immunoregulatory responses during infection." (PMID 41753558, 2026).
infection (continued). "The mRNA abundance of TNF-α, IL-1β and IL-6 were significantly up-regulated from 6 h to 24 h post infection, while those of iNOS, Arg-1 and IL-10 did not change significantly from 18 h to 24 h post infection." (PMID 40663568, 2025). "In comparison, only modest effects were observed when IL1B was added during or after infection, presumably because the induction of an antiviral state requires de novo synthesis of antiviral factors." (PMID 40442100, 2025). "In control macrophages, both HN878 and CDC1551 infections significantly increased the levels of proinflammatory (TNFα, IL1β, IL6, and CXCL8) and anti‐inflammatory (IL4 and IL10) molecules and GMCSF." (PMID 41287823, 2025). "It is involved in innate immunity following infection, which can trigger the release of pro-inflammatory cytokines such as IL-1β." (PMID 40895561, 2025). "Pre-treatment of HEK293T-ACE2 cells with different concentrations of IL-1β for 1 hr, then inoculated with 0.5 multiplicity of infection (MOI) Delta or wild-type (WT) authentic SARS-CoV-2 virus." (PMID 39937682, 2025). "It was observed that expression of TNF-α and IL-1β significantly enhanced at early time points (24 and 48 h) post-infection." (PMID 40982322, 2025). "The expression of serum IL-1β was higher on day 6 post-infection than on days 2 and 4 in both groups of mice, though the differences were not statistically significant." (PMID 40377310, 2025). "Analysis revealed that TNF-α and IL-1β, important pro-inflammatory cytokines, gradually increased on different days post-infection (1, 3, 7, 15 dpi), peaking at 7 dpi." (PMID 39799330, 2025). "The cytokine IL‐1β is a driver of the fever response, controls immune cell recruitment and activation, induces an interferon‐like state at the site of infection, and can restrict the formation of syncytia between cells to restrict virus transmission." (PMID 39878363, 2025). "This response involves the production of cytokines such as TNF-α, IL-1β, and IL-6, which recruit immune cells like neutrophils and macrophages to the site of infection." (PMID 39792889, 2025). "This process highlights the role of neutrophils as the dominant source of IL-1β in murine models of infection by S. pneumoniae." (PMID 41087719, 2025). "In our study, in women with PCOS and confirmed infection with any atypical pathogen (n = 196), we analyzed the levels of proinflammatory cytokines, such as IL-1β, IL-6 and TNF-α, which are important in this type of infection." (PMID 40647668, 2025). "Similar to our findings in non-infected mice and murine BMDMs, Agmo deletion had little effect on cytokine transcription in adipose tissue under infection, except for a clear trend towards higher Il-1b and Tnfa levels in female KO BAT samples." (PMID 40474257, 2025). "IL-1β, a pro-inflammatory cytokine, plays a critical role in initiating inflammatory responses to tissue damage and infection." (PMID 40988268, 2025). "M1 macrophages are activated during the acute infection phase, releasing cytokines like TNF‐α, IL‐6, and IL‐1β to control infection." (PMID 40060195, 2025). "Although the mRNA and protein levels of IL-1β were not significantly decreased during IAPA compared to singular infection with A. fumigatus, there was a clear trend toward the inhibition of IL-1β during IAPA." (PMID 39949778, 2025). "Interaction between breed and infection was observed, the IL-1β being higher in Modicana breed than in Simmental and Holstein when infection was present." (PMID 40302747, 2025). "The production of IL-1B is important for the development of antibiotic-adaptive immunity in the early stages of infection." (PMID 40725488, 2025). "The mechanism of macrophage cell infection appeared to be linked to dynamic ACE2 expression and depended upon IL-1β-driven NF-κB transcription of hACE2." (PMID 39763770, 2025).